CCL5 (C-C motif chemokine ligand 5)
Diseases named in the same sentence as CCL5 in open-access papers (continued):
Sharing a sentence is not in itself a finding about the gene and the disease.
tumor (continued). "We found that tumors of the different ZHENG models exhibited significantly altered cancer-associated fibroblast (CAF) proliferative activity and tumor-associated macrophage (TAM) infiltration, which led to altered levels of CAF- and TAM-derived secreted cytokines such as SDF-1 and CCL5." (PMID 22690248, 2012). "CCL-5 might provide a supporting environment for tumor growth by recruiting leukocytes, such as monocytes and T cells to the tumor." (PMID 23342280, 2012). "The higher intratumoral CCL5 levels after α-TEA treatment may contribute to the attraction of T cells to the tumor bed, as has been shown for inflammatory sites, including tumor sites." (PMID 21232138, 2011). "In addition, vaccination allowed to increase the protective action of CCL5 blockade from 30% to 40% and to reduce tumor incidence from 100% to 60% in mice." (PMID 22205974, 2011). "Furthermore, these results suggest that in this specific sub-group of IDC-with-relapse patients, the two cytokines are coordinated with other tumor-supporting factors that replace CCL2 & CCL5 in promoting disease relapse." (PMID 21486440, 2011). "Although 100% of the mice from both groups developed liver tumors, there was a significant reduction (30%) in the overall tumor load in the livers of the anti-CCL5-treated mice compared to the control group, as assessed by measuring liver weight (1.24 vs 1.78, P<0.05)." (PMID 22205974, 2011). "Significant associations were found between CCL2 & CCL5 and TNFα & IL-1β in the tumor cells in DCIS and IDC-no-relapse patients." (PMID 21486440, 2011). "Under such conditions, TNFα & IL-1β would not act on the tumor cells to promote the release of CCL2 & CCL5, leading to lack of associations between the two cytokines and CCL2 & CCL5." (PMID 21486440, 2011). "Indeed, our data indicate that administration of CCL5-directed antibodies into mice led to an accumulation of leukocytes within the cancer stroma as well as at the interface tumor-parenchyma." (PMID 22205974, 2011). "Furthermore, α-TEA treatment modulated the tumor microenvironment in a proinflammatory fashion, as we found significantly higher IL-6 and CCL5 levels and a trend toward higher levels of other proinflammatory mediators (IL-1β, CCL2, CCL3, CCL4)." (PMID 21232138, 2011). "CCL5 can mediate tumor cell survival, cell growth and metastasis in a number of malignances." (PMID 21631947, 2011). "Furthermore, an inverse correlation between tumoral CCL5 expression and number of macrophages in the tumor microenvironment has been reported, which suggests an antitumoral, rather than a protumoral, role of CCL5." (PMID 22162712, 2011). "CCL5 is also proposed as a natural adjuvant to boost anti-tumor immunity." (PMID 21631947, 2011). "In addition, we demonstrate that both IL-6 and CCL5 promote the proliferation of LNCaP tumour cells reaching their maximal activity synergistically." (PMID 19242540, 2009). "One key inflammatory component to tumor sustenance first discovered in the late 1970s is the infiltration of tumor-associated macrophages (TAM) which are attracted by monocyte chemotactic protein (MCP-1), RANTES and CCL5." (PMID 19183457, 2009). "Proliferation assays were then carried out to evaluate whether the increased availability of IL-6 and CCL5 in a neoplastic microenvironment would affect the growth of the LNCaP tumour cell line." (PMID 19242540, 2009). "Mast cells might be specifically attracted to the tumor area by chemokines produced by H/RS cells and studies revealed several chemokines in HL lines among which CCL5 (RANTES)." (PMID 19623262, 2009). "Additionally CCL5 promote the growth of CAFs, that is responsible for tumor growth and metastasis." (PMID 40297849, 2025). "Additionally, our speculation on the primary regulatory pathway of CCL5 offered insights into potential therapeutic strategies for reinvigorating exhausted T cells in the tumor microenvironment of GBM." (PMID 41155216, 2025).
tumor (continued). "In addition, CCL5 may also support tumor growth through the promotion of angiogenesis and the enhancement of tumor cell migration and metastasis." (PMID 41376630, 2025). "Our findings reveal the critical role of cGAS-STING in mediating the secretion of CCL5, which facilitates intercellular communication between tumor cells and stromal cells during cisplatin treatment, although we do not exclude the possibility that other pathways may also contribute." (PMID 41152972, 2025). "Finally, the expression of CCL5 by tumor-specific and stem-like TCF+ T cells and NK may increase the recruitment of additional T cells." (PMID 40027748, 2025). "Compared with lung adenocarcinoma (LUAD) and lung squamous cell carcinoma (LUSC), SCLC exhibits a markedly lower infiltration of CD8+ T cells, which may partly stem from reduced expression of the chemokine CCL5—a critical mediator of immune cell recruitment to the tumor microenvironment." (PMID 41194225, 2025). "Furthermore, CCL5 upregulates PD-L1 expression on tumor cells, inducing immune evasion." (PMID 41154598, 2025). "Moreover, the expression of chemokines such as CCL3,CCL4, and CCL5 may influence T cell recruitment and localization, further exacerbating the immunosuppressive state in the tumor microenvironment." (PMID 41394809, 2025). "In addition to its well-documented involvement in promoting tumor cell migration and invasion, CCL5 may also enhance anti-tumor immune responses by modulating immune activity and promoting immune cell infiltration." (PMID 40496857, 2025). "In addition, the tumor-immune correlation analysis demonstrated that PHF8 expression was strongly negatively associated with the levels of MHC class I genes including B2M, HLA-A/B/C, TAP1/2 as well as chemokines such as CCL5 and CXCL10." (PMID 40001243, 2025). "Furthermore, in a xenograft model, CCL5 overexpression enhanced vascularization and tumor growth through the downregulation of miR-199a, whereas CCL5 deletion led to increased miR-199a levels, reduced VEGF expression, impaired angiogenesis, and suppressed tumor progression." (PMID 40429954, 2025). "Myeloid cells were subclustered into monocyte, Tumor-associated macrophage (TAM) including SPP1+ TAM, C1Qs+TAM, HSPs+ TAM, ACP5+ TAM, and CCL5+ TAM, classical dendritic cell (cDC) encompassing cDC, CD1A+ DC, LAMP3+ DC and PCLAF+ DC, plasmacytoid DC (pDC) as well as unknown subpopulations." (PMID 40904511, 2025). "Notably, Vegfa macrophages and Proinflammatory macrophages exhibited downregulation of tumor angiogenesis and protumorigenic genes (e.g., Cxcl3, Cxcl1, S100a8, SPP1) and upregulation of immune cell recruitment‐associated genes (e.g., Cxcl9, Ccl5, Ccl8) in mRNA‐treated groups." (PMID 39761175, 2025). "With this approach, we characterize single-cell production of Ifnb1, Xcl1 and Ccl5 in mouse tumors and identify monocytes and monocyte-derived macrophages as the main producers of type I interferon transcript Ifnb1 consistent across 4 different syngeneic tumor models." (PMID 39372774, 2024). "Furthermore, CCL5 positivity in ICs was associated with a 1.93-fold, 1.87-fold, 3.52-fold, and 2.21-fold increased risk of tumor-associated death for patients with tumor stage pT3 + 4, nodal stage N0, nodal stage NX, or no chemotherapy, respectively." (PMID 38928033, 2024). "However, we did not detect differences in the mRNA levels of these factors between tumors with and without mitofusin 1, maybe because other immune cells present in the tumor can also express Ccl5 and Lgals9." (PMID 38195762, 2024). "A study demonstrated that in the presence of CCL5 within tumor islets, a known attractant for T cell migration, despite the stroma showing a fivefold higher T cell infiltration per unit volume compared to the tumor islets, T cells were still able to infiltrate into the tumor islets." (PMID 39513932, 2024). "However, CCL5 also facilitates the infiltration of CD8+ T cells to kill tumor cells." (PMID 39507529, 2024).
tumor (continued). "However, CCL5 can also suppress T cell immunity at the tumor site and may even promote tumor immune evasion by inducing tumor infiltration by regulatory T (Treg) cells, impairing the cytotoxic activity of CD8+ T cells." (PMID 39114657, 2024). "In addition, CCL5 may also recruit immunosuppressive Tregs and Th2 cells to further promote tumor progression." (PMID 37669110, 2023). "In addition, the CCL5/CCR5 axis is the main actor during tumor progression." (PMID 37040518, 2023). "However, methylation of CCL5 mRNA in most tumor cells leads to decreased expression of CCL5." (PMID 37660142, 2023). "This suggests CCR5 antagonist treatment may be a promising approach to reduce tumor growth in other solid tumors in which CCL5 plays a pro-tumoral role, such as PCa, where Maraviroc was shown to reduce bone metastasis of intracardially injected PCa cells in mice." (PMID 37025604, 2023). "Collectively, therefore, CCR5-targeted therapy will be an effective treatment for patients with cancers that express high levels of CCR5/CCL5 and high levels of circulating tumor cells and/or metastases, and may be well positioned to augment the efficacy of current therapies." (PMID 37759462, 2023). "Notably, in addition to CCL5, tumor-autonomous CD73 may upregulate other molecules involved in maintaining an immunosuppressive microenvironment via its noncanonical function." (PMID 37291128, 2023). "CCL2, also known as monocyte chemoattractant protein-1, and CCL5, also referred to as RANTES (regulated on activation, normal T cell expressed, and secreted), are key molecules in macrophage chemotaxis and activation that have been reported to promote tumor proliferation." (PMID 36571444, 2023). "Therefore, cancer cells overexpressing A3A augment anti-tumor immune response might by secreting CCL5 and CXCL10 to recruit and activate CD8+ T cells in ESCC, which warrants further functional investigations." (PMID 37215984, 2023). "In addition, as a TAM mediator, CCL5 promotes tumor proliferation, invasion and metastasis." (PMID 36173487, 2023). "CD8+ TMs expressing CCL5 and GZMA, MAIT (mucosal‐associated invariant T) cells expressing TCF7 and PLAC8, and CD4+ TNs (Naïve T cells) expressing CCR7 appeared in paratumour tissues, while CD4+ISG+ T cells expressing ISG15/20 and CD8+ TNs expressing TCF7 only appeared in tumour tissues." (PMID 36855810, 2023). "However, CCL5 and anti-CCL5 antibodies rarely affect the tumor-inhibiting effect induced by PTBP2, leading us to hypothesize that PTBP2-attracted monocytes and Mφs may exert their main antitumor effects through other mediators." (PMID 37040518, 2023). "Moreover, CCL5 from tumor buds recruitment fibroblasts by acting on CCR5 receptors on fibroblasts." (PMID 37141250, 2023). "In addition, the expression of CCL5 in tumor tissues of patients with CRC may promote tumor invasion and lymph node metastasis." (PMID 37141250, 2023). "Interestingly, CCL5 blockade significantly inhibited CD73 overexpression-induced tumor progression." (PMID 37291128, 2023). "Expression of the chemokines Cxcl7 and Ccl5 was significantly elevated, and Cxcl2 and Cxcl12 trended upward in H1792ΔSTK11 tumors compared with control tumors when using mouse primers, concordant with the observed changes in tumor immune cellularity and consistent with host responses." (PMID 37092555, 2023). "The CCL5/CCR5 axis has also been reported to be engaged in the activation of several signaling pathways, including JAK/STAT, PI3K/AKT/mTOR, HIF‐α, TGF‐β‐smad, and NF‐κB axes that are implicated in inflammation, angiogenesis, tumor cell proliferation, apoptosis, and metastasis." (PMID 35702353, 2022). "Collectively, CCL5-deficiency could enhance the antitumor activity of MDSC-DCs as tumor vaccine and ATRA could not only increase the differentiation of MDSC-DCs but also have a synergistic effect with CCL5-deficiency on boosting the tumor inhibition activity of MDSC-DCs." (PMID 35707772, 2022).
tumor (continued). "Similarly, the designed targets CD19 and BCMA were efficiently expressed and delivered at HEp-2 cell surface from 4 h p.i. to 96 h p.i., which indicated that T7011 infection can deliver and display the CAR targets on the tumor cell surface, as well as the release of CCL5 for up to 4 days." (PMID 36353540, 2022). "In addition to tumor cells, CCL5 is also expressed on T cells." (PMID 36033472, 2022). "Thus, the Ccl5-Ccr5 axis was promoted by Cd8+ T cells-NK cells interactions and NK cells-NK cells interactions, which significantly enhance tumor infiltration and anti-tumor effects of NK cells." (PMID 36438484, 2022). "CCL5 may serve as a potential diagnostic marker and therapeutic target for CRC tumor germination." (PMID 36387070, 2022). "Furthermore, among the mice treated with the combination therapy, levels of Th1 cytokine IFNγ and T-cell-recruiting chemokine CCL5 in the tumor were significantly lower in the B cell KO mice than in the WT mice, whereas the level of VEGF was significantly higher in the B cell KO mice." (PMID 35720386, 2022). "It was suggested that the CCR5/CCL5 pathway may play a role in tumor suppression." (PMID 35404390, 2022). "TAMs could independently stimulate tumor cell growth and migration via the CCL5/CCR1/CCR5 axis." (PMID 35646059, 2022). "Moreover, CCL5 could increase the number of α-SMAhigh CD90high FAPlow fibroblasts and thus promote tumor angiogenesis by enhancing VEGFA expression and making fibroblasts transdifferentiate into vascular endothelial cells." (PMID 35241150, 2022). "Hence, we suggested that the up-regulated expression of CCL22 and CD206 in CCL5−/− mice after cryo–thermal therapy could play a positive role in anti-tumor activity of macrophages." (PMID 35327361, 2022). "Finally, the results also showed that CCL5 could promote collagen synthesis through fibroblasts, thus contributing to tumor progression." (PMID 35241150, 2022). "Based on these findings, we speculated that tumor bud-derived CCL5 increased the number of α-SMAhigh CD90high FAPlow fibroblasts and promoted tumor angiogenesis via the increase in VEGFA and the transdifferentiation of fibroblasts into vascular endothelial cells." (PMID 35241150, 2022). "Furthermore, there was a linear positive correlation between CCL5 in serum and tumor tissue." (PMID 36033472, 2022). "Conversely, according to other studies, PARP inhibition has been shown to induce cytosolic DNA accumulation and type I IFN response, along with increased intra-tumor CD8+T cell infiltration dependent on C-C chemokine ligand 5 (CCL5) and CXCL10 chemokines, irrespective of the BRCA mutational state." (PMID 36428727, 2022). "Finally, to ascertain whether the CCL5 that recruits fibroblasts was secreted by CRC tumor cells, CCL5 knockdown and overexpressing cell lines were established using siRNA and lentiviral constructs, respectively." (PMID 35241150, 2022). "Therefore, we speculate that the METTL14/CCL5/Tregs axis might be a potential pivotal regulated pathway of tumor immunity and progression in ccRCC, a subject worthy of further in-depth study." (PMID 34122497, 2021). "Indeed, it has been reported that CCR5 and CCL5 might have relevant role in the angiogenic mechanism during tumor cells evasion through the recruitment of inflammatory cells." (PMID 34976001, 2021). "The reduced Ccl5 secretion associated with Glipr1 knockdown led to reduced tumour infiltration by inflammatory macrophage and CD8+ T cytotoxic T cells, thereby aiding tumour immunity, as infiltration by these immune cells is usually associated with reduced tumour growth." (PMID 34572888, 2021). "In addition, CCL5 expressed by cancer cells plays an important role in remodeling the tumor microenvironment, whether circETFA can participate in regulating tumor immune evasion by regulating CCL5 is also worthy of investigation." (PMID 34716323, 2021).
tumor (continued). "Moreover, HIF‐1α in fibroblasts could activate the NF‐κB signalling pathway and enhance a subsequent secretion of CCL5, thus promoting the tumour growth." (PMID 33943003, 2021). "Thus, we hypothesize that in the therapeutic setting, exogenous CCL5 primarily recruits cells that are able to participate in an anti-tumor immune response in the presence of anti-PD-L1." (PMID 34030676, 2021). "Furthermore, overexpression of CCL5 promotes tumour growth and disease progression." (PMID 34638423, 2021). "Moreover, the genes associated with T cell function (e.g., perforin and IFN-γ) and T cell recruitment (e.g., CCL5) were enriched within the tumor and the level of IFN-γ and TNF-α in plasma after treatments was elevated, especially following the combined treatment." (PMID 34307367, 2021). "Although we have not looked at an absolute requirement for CCL5 expression in the control of SCC in the present study, it is interesting to speculate that CCL5 may also be responsible for the small but detectible numbers of CD8 T cells present within the tumours of anti-CXCR3-treated mice." (PMID 33925140, 2021). "Stromal CCL5 immunoreactivity was significantly correlated with the histological grade and MVD and tended to be correlated with Ki67, a cell proliferation marker, and negatively correlated with the ER and PR and suggested to be associated with tumor growth, invasion and angiogenesis." (PMID 33671956, 2021). "For example, tumor-derived PAI-1 promotes the migration of monocytes and polarizes tumor-associated macrophages (TAMs) towards proinflammatory phenotypes, leading to the production of proinflammatory and angiogenesis-promoting factors such as IL-1, IL-8, CCL2, CCL3, CCL5, and VEGF." (PMID 34912726, 2021). "Also, a role for “patrolling” monocytes (PMo) in regulating NK cell anti-tumor activity has been delineated in a murine model of lung cancer where PMo induced NK cell recruitment through secretion of high levels of CCL3, CCL4, CCL5 and their activation in the tumor site." (PMID 34975880, 2021). "Interestingly, BrCa cells stimulate CCL5 production by MSCs, which in turn stimulates tumor growth, invasion, and metastasis, a process that may occur in bone metastasis, too." (PMID 34064859, 2021). "TAK‐779 is an inhibitor of CCR5, which could inhibit the effect of CCL5 on tumour cells." (PMID 33943003, 2021). "CXCL9-CXCR3 interaction and CCL5 are crucial for T cell function and infiltration into tumors, and higher level of expression of these genes might result in improved anti-tumor immunity in patients with better survival outcomes." (PMID 33834038, 2021). "Pathogenic microorganisms and tumor cells can be eliminated by M1 macrophages by acute proinflammatory response, immune activation reaction, and cytophagy through the release of proinflammatory factors, such as NO, IL-1β, IL-6, TNF-α, and chemokines such as CCL2, CCL3, CCL5, CXCL9, and CXCL10." (PMID 34506209, 2021). "Thus, CCL5 may have a different role in controlling the makeup of the tumor microenvironment in developing versus established tumors, especially in the context of immunotherapy." (PMID 34030676, 2021). "In addition, CCL5 is also responsible for the maintenance of tumor cells within the TME43,44." (PMID 34433873, 2021). "Additionally, CCL5 produced by immune cells can promote tumor growth and proliferation by regulating macrophage production of metalloproteinases or inducing epithelial–mesenchymal transformation in tumor cells." (PMID 34531849, 2021). "It has been proposed that CCL5/CCR5 axis may promote tumor development in multiple ways, such as growth factors, stimulating angiogenesis, regulating the extracellular matrix, inducing recruitment of additional stromal cells and inflammatory cells, and participating in immune evasion mechanisms." (PMID 34777462, 2021).